FAM149A (family with sequence similarity 149 member A)
Synonyms: MST119; DKFZP564J102; MSTP119
Tractability: No criterion of Open Targets' tractability assessment is met for any kind of drug.
Gene: Protein-coding gene on chromosome 4 (186,104,419 to 186,175,337, forward strand). Ensembl gene ENSG00000109794.
Subcellular location (Human Protein Atlas): Golgi apparatus
Genetic constraint (gnomAD): Loss-of-function variants: 62 observed, 70.78 expected, observed/expected ratio (o/e) 0.88, 90% interval 0.71 to 1.08. The upper end of that interval is the gene's LOEUF score, 1.08, which puts it in group 4 of 6, group 1 being the genes least tolerant of losing a copy. Missense variants: 994 observed, 911.65 expected, observed/expected ratio (o/e) 1.09, 90% interval 1.03 to 1.15. Synonymous variants: 432 observed, 379.96 expected, observed/expected ratio (o/e) 1.14, 90% interval 1.05 to 1.23.
Homologues: Orthologues: chimpanzee FAM149A (97% identical), macaque FAM149A (91% identical), rabbit FAM149A (69% identical), mouse Fam149a (63% identical), rat Fam149a (55% identical), guinea pig FAM149A (55% identical), tropical clawed frog fam149a (41% identical), dog FAM149A (34% identical), zebrafish fam149a (25% identical). Paralogues in human: FAM149B1 (18% identical).
Diseases named in the same sentence as FAM149A in open-access papers:
FAM149A is named in the same sentence as 1 disease in open-access papers, as found by Europe PMC text mining. Sharing a sentence is not in itself a finding about the gene and the disease. The quoted sentences say what the papers report.
brain disease (1 paper, 2023). "Many of these 3′aQTLs were associated with important brain disease-related genes, such as FAM149A for Glass Syndrome43 and MAPT (encoding tau protein) for PD and AD." (PMID 36737438, 2023).